LOX (lysyl oxidase)
Diseases named in the same sentence as LOX in open-access papers (continued):
Sharing a sentence is not in itself a finding about the gene and the disease.
tumor (continued). "LOX enzymes are found in immunological, epithelial, and tumor cells and they perform a range of roles in the body, including inflammation, skin disorders, and carcinogenesis." (PMID 36296501, 2022). "Methylated bands were faint in tumor tissues and more pronounced in normal tissues, thus confirming the low methylation level of LOX in tumors compared to normal tissues." (PMID 36090891, 2022). "have found that CAFs-derived lysyl oxidase (LOX) facilitated the Warburg effect of tumor cells and increased the flux of glycolysis." (PMID 36439439, 2022). "The physics of the tumor stroma is regulated by collagen fiber cross-linking, which is catalyzed by lysyl oxidase (LOX)." (PMID 36276147, 2022). "As the major source of ECM, CAFs further modify the tumor mechanical environment by expressing lysyl oxidase (LOX), an amine oxidase that initiates the process of covalent intramolecular and intermolecular crosslinking of collagen." (PMID 35372359, 2022). "Recently, it was found that mesenchymal stromal cells expressing meflin, a glycosylphosphatidylinositol-anchored protein, showed tumor-suppressing effects by reducing LOX activity in the tumor stroma." (PMID 35205794, 2022). "Collagen cross-linking is principally by lysyl oxidase (LOX) contributing to tumor progression, the inhibition of which suppresses fibrosis and increases tumor dormancy." (PMID 36276103, 2022). "CAFs as the major source of the ECM, remodify the tumor microenvironment by expressing lysyl oxidase (LOX) that initiates the crosslinking of collagen upon tumor progression, which is closely related to the ECM density and composition." (PMID 36419159, 2022). "LOX enzymes can also remodel the TME and have been implicated in all stages of tumor initiation and the progression of many cancer types." (PMID 36421795, 2022). "Scientific evidence demonstrates that LOX can have both tumor suppressor and metastasis enhancer activities." (PMID 35625590, 2022). "By contrast, the unique propeptide derived from pro-LOX (LOX-PP) has tumor growth inhibitory properties consistent with being a tumor suppressor." (PMID 35563478, 2022). "Further studies should be completed in tumor subtype or other treatments to raised test a prognostic role and to verify applicability of thresholds of cfDNA integrity or LOX activities values." (PMID 35189882, 2022). "Along with increased collagen deposition, an overexpression of lysyl-oxidase (LOX) enhances collagen crosslinking, creating a dense and stiff microenvironment characteristic of tumor stroma fibrosis." (PMID 35269922, 2022). "Different from other oxidases, the in situ lactate oxidase (LOx) catalysis display high efficiency due to the abundant lactate substrate in the hypoxia tumor microenvironment (TME) and the ultralow O2 reaction threshold." (PMID 36144938, 2022). "Following these observations, additional evidence has accumulated suggesting that lysyl oxidases, such as LOXL2 and LOX, promote desmoplasia under various conditions and, as a result, promote tumor cells invasiveness and tumor metastasis." (PMID 35682926, 2022). "The secretion of lysyl oxidase (LOX) by tumor cells initiates lysine-derived collagen cross-linking, thereby stiffening the tumor stroma." (PMID 36291542, 2022). "Cleavage by the BMP-1 protease also released the catalytically inactive N-terminal LOX-PP peptide, which functions as an inhibitor of the ras signal transduction pathway and as a tumor suppressor." (PMID 36232621, 2022). "This is supported by data linking expression dysregulation of LOX enzymes with metastasis and tumour survival rates in some cancers." (PMID 35800439, 2022). "In metastatic breast cancer, the active LOX, typically found mainly outside the tumor cells, shows aberrant intracellular localization and enhances Akt, Erk, and NF-κB activities, promoting tumor proliferation and migration." (PMID 36293126, 2022).
tumor (continued). "In GC liver metastasis, the expression of LOX in CAFs was up-regulated, which promoted the proliferation of tumor cells and suggested a poor prognosis." (PMID 36439439, 2022). "Following cleavage by BMP-1, the cleaved N-terminal part, also known as pre-pro LOX (LOX-PP), functions as an inhibitor of tumor progression." (PMID 35682926, 2022). "In this context, enzymes secreted by tumor cells, such as lysyl oxidases (LOX), are capable of crosslinking collagen and, thus, to building up one collagen I structure that promotes metastasis." (PMID 36139572, 2022). "Taken together, our results demonstrate that the lysyl-oxidase-independent effects of L2Δ13/LOXL2 contribute to tumor progression via enzyme mobilization and enhanced glycolysis." (PMID 36209516, 2022). "Genetic depletion of LOX in the primary tumor (via shRNA-mediated LOX knockdown in implanted 4T1 cells), or systemic administration of LOX neutralizing antibodies, reversed osteolytic lesion formation and normalized osteoclast differentiation and function." (PMID 35804902, 2022). "It has been demonstrated that pyruvate dehydrogenase kinase 1 (PDK1) and lysyl oxidase (LOX) were associated with chemoresistance, tumor metastasis, and poor survival." (PMID 36204682, 2022). "Kruskal–Wallis test showed that: DNA methylation level of LOX is corelated with tumor stage (stageII vs stageIV, stageIII vs stage IV) (all p < 0.05)." (PMID 36202905, 2022). "LOX enzymatic activity is reported to drive tumour angiogenesis by activating PDGFRβ signalling in vascular SMCs, which is consistent with our DEG analysis that FL SMCs expressed PDGFRB at high levels." (PMID 35332263, 2022). "Thereby, the complexity emerging from that intricacy “precludes traditional microarray-based research to investigate tumor suppressor/metastatic promoting functions of LOX in human cancers”." (PMID 35625590, 2022). "Ionizing radiation can induce tumor cells to secrete LOX and enhance the invasive ability of naive tumor cells." (PMID 36293126, 2022). "According to a number of studies, LOX has been highlighted as a biomarker of tumor progression and metastasis in multiple cancers, such as colorectal, breast, and ovarian carcinomas, as well as bronchial cancers." (PMID 36202905, 2022). "In a study by Levental and colleagues, overexpression of LOX in the mammary glands of MMTV-Neu mice lead to increased tumour growth with more invasive properties." (PMID 35160252, 2022). "The five lysyl-oxidase genes share similar enzymatic activities and contribute to tumor progression." (PMID 36232621, 2022). "They proposed that tumour-derived growth factors (VEGF, Lysyl Oxidase) released by disseminated tumour cells (DTCs) act for the purpose of ‘priming’ the bone ECM to facilitate a more favourable microenvironment for DTC attraction, survival and proliferation." (PMID 35754558, 2022). "The in situ lactate oxidase (LOx) catalysis is highly efficient in reducing oxygen to H2O2 due to the abundant lactate substrate in the hypoxia tumor microenvironment." (PMID 36144938, 2022). "Additional critical roles have been shown for LOX/LOXL in both cancer-associated fibroblasts (CAFs) and fibrocyte-mediated regulation of the tumor microenvironment." (PMID 35205728, 2022). "Mechanically, LOX regulated the function of CAFs and macrophage polarization to remodel the tumor immune microenvironment." (PMID 35966586, 2022). "In experimental models, inhibiting matrix stiffening via LOX inhibition ameliorates tumor growth and improves therapy." (PMID 35372359, 2022). "Additional studies demonstrating nuclear activity of LOX focused on its’ tumor-suppressor properties in the ras-transformed cells, RS485 (NIH 3T3 transformed by c-H-ras), cells which normally express low LOX levels." (PMID 36232685, 2022). "Collagen crosslinking by LOX is also crucial for matrix stiffening and increases tumor incidence in a mouse model." (PMID 35205794, 2022).
tumor (continued). "High mRNA levels of LOX and LOXL2 were associated with advanced PDAC stage, while elevated LOX and LOXL3 expression correlated with high tumor grade." (PMID 35433829, 2022). "Overexpressed in tumor matrix were proteins involved in ECM organization such as LOX, LAMB3, ADAMTSL1 and FBN2." (PMID 35340765, 2022). "LOX-PP–Hsp70–cRaf interactions resulted in reduced Erk1/2 signaling, which is Ras/c-Raf pathway-dependent, and consistent with the tumor growth inhibitory properties of LOX-PP." (PMID 35563478, 2022). "But the expression of LOX was negatively correlated with tumor depth of invasion, which has also been reported in clinical studies." (PMID 36202905, 2022). "Reduction of ECM through lysyl oxidase (LOX) inhibition in mouse models led to accelerated tumor growth." (PMID 34692532, 2021). "Altered mechanical properties derive partly from the more linearized and crosslinked nature of collagen I at the tumor-stroma interface, as a result of HIF1α-induced elevated lysyl oxidase (LOX) activity." (PMID 34768998, 2021). "The crosslinking of collagen and elastin facilitated by LOX enhances the proliferation of tumor cells and promotes metastatic colonization and a fibrotic microenvironment that improves the survival of tumor cells, supporting the development of metastasis." (PMID 34815382, 2021). "We assume that it is during early tumor stages and the construction of fibrous stroma that LOX activity is the highest." (PMID 34106045, 2021). "Effect of LOX inhibition on tumor stiffness and tumor stroma organization in EGI-1, KPC, MMTV-PyMT, and mPDAC tumor models." (PMID 34106045, 2021). "In consideration of this concern that tumor cells can modify the tumor immune microenvironment by activating immune checkpoints, we therefore analyzed the correlations between LOX expression and several immune checkpoints." (PMID 35047494, 2021). "In particular, enhancements of T cell displacements were noticed in all tumor models under LOX inhibition." (PMID 34106045, 2021). "The Kaplan‐Meier survival analysis showed that higher expression of LOX in tumor stroma had an adverse prognostic impact on the OS of OSCC patients (P < 0.001)." (PMID 34930321, 2021). "It paves the way for clinical trials combining LOX inhibitors with PD-1/PD-L1 blockade, possibly in biomarker-selected cohorts of patients with high tumor stiffness evaluated with non-invasive imaging approaches such as SWE." (PMID 34106045, 2021). "The lysyl oxidase (LOX) family of enzymes underpin the fibrotic remodeling of the tumour microenvironment to promote both cancer growth, spread throughout the body and modulate response to therapies." (PMID 33513979, 2021). "Despite comprehensive efforts to identify the roles of LOX in the tumor microenvironment, sensitive and accurate detection methods have not yet been established." (PMID 34572752, 2021). "In another study, it was shown that reduction of tumor stiffness in mice using a LOX-inhibitor increased the number of tumor-infiltrating T cells and improved the response to anti-PD-1 therapy." (PMID 34956223, 2021). "In the cellular complexity of a tumor, it has been demonstrated that LOX can be expressed either by stromal or epithelial cells, in the latter case, associated with a malignant phenotype." (PMID 33946660, 2021). "In the ECM of tumor tissues, LOX induces the cross-linking of collagen, contributing to an increase in the ECM stiffness." (PMID 34572752, 2021). "Lysyl oxidase (LOX) is an ECM remodeling enzyme that is abundantly expressed in the tumor microenvironment." (PMID 34572752, 2021). "Overall, while ECM and stiffness normalization achieved through LOX inhibition increases T cell infiltration and migration, this strategy also improves the efficacy of anti-PD-1 blockade on tumor growth." (PMID 34106045, 2021). "Although not dealing with anti-PD-1 treatment, several articles are consistent with the notion that LOX inhibition is more effective in early tumor stages." (PMID 34106045, 2021).
tumor (continued). "In this study, we utilized LOX-sensitive hexapeptides (LS-peptides) to functionalize AuNPs as a colorimetric sensor to detect LOX both in vitro and in tumor tissue extract." (PMID 34572752, 2021). "For example, collagen is crosslinked and degraded in the tumor niche by enzymes such as lysyl oxidase and matrix metalloproteinases." (PMID 34485136, 2021). "It has been well documented that LOX family members, especially LOX and LOXL2, are elevated and associated with tumor progression." (PMID 33883562, 2021). "Recent studies have shown that factors secreted by the primary tumor, such as LOX, MMPs and exosomes, initiate the formation of this niche even before the dissemination of tumor cells." (PMID 34298680, 2021). "This confirms that the high heterogeneity in local tissue mechanical properties of KPC tumor can be reduced upon treatment with a LOX inhibitor." (PMID 34106045, 2021). "When the LS-AuNPs were applied to various tumor tissue extracts, the LOX levels correlated directly with their collagen content and ECM stiffness." (PMID 34572752, 2021). "The lysyl oxidase (LOX) family and MMPs represent two major types of remodeling enzymes produced by CAFs with a high relevance in tumor progression." (PMID 34356110, 2021). "Metastasis of any tumor is characterized by the secretion of proteolytic enzymes such as matrix metalloproteinases (MMPs) and lysyl oxidase (LOX), capable of degrading the extracellular matrix (ECM) and basement membrane." (PMID 34815382, 2021). "Similar results have also been confirmed in our research, however, one study indicated that LOX expression was downregulated in GC, and LOX functioned as a tumor suppressor." (PMID 35126449, 2021). "LOX is a secreted amine oxidase that modifies the primary tumor microenvironment by crosslinking collagen and elastin in the ECM and has been linked to metastasis of CRC cells such as SW480 and its patient-matched metastatic clone, SW620." (PMID 34356110, 2021). "The dramatic effects of the treatment with the LOX inhibitor BAPN on ER signaling highlight how this tumor subtype specifically relies on the interaction with the ECM." (PMID 33616307, 2021). "Lastly, studies have directly or indirectly investigated the effects of LOX-mediated collagen cross-linking on tumor growth in mice." (PMID 34956223, 2021). "To further illustrate the correlation between LOX and tumor immune microenvironment, we evaluated the relationship of LOX and six types of immune-infiltrating cells in TIMER database." (PMID 35047494, 2021). "To investigate the expression of LOX in tumor stroma, we also evaluated the expression of LOX and CAFs markers α-SMA and FAP in OSCC clinical samples by multiplex IHC staining." (PMID 34930321, 2021). "These same signaling pathways activate tumor cell invasion, since LOX inhibition using β-aminopropionitrile (BAPN) was shown to abrogate cervical carcinoma cell invasion and migration." (PMID 34298680, 2021). "To confirm these observations in vivo, we used a xenograft model and added the LOX recombinant protein before and after the tail vein injection of tumor cells to observe the potential effect of LOX on tumors." (PMID 35003355, 2021). "The LOX levels, which were measured using LS-AuNPs in various tumor tissue extracts, correlated directly with their collagen contents." (PMID 34572752, 2021). "AuNPs functionalized with LOX-sensitive hexapeptides were introduced to detect LOX levels as a colorimetric sensor in vitro as well as in tumor tissue extracts." (PMID 34572752, 2021). "Distinct color changes and spectral shifts in the plasmon band were observed in the LS-AuNPs treated with the tumor lysates of MDA-MB-231 tumors in comparison with the MCF-7 or MDA-MB-231 tumors treated with LOX inhibitors." (PMID 34572752, 2021). "High LOX and LOXL2 expression is considered a risk factor for the early occurrence of metastases, mostly due to their ability to stimulate tumor cell migration and invasion." (PMID 33669630, 2021).
tumor (continued). "TGF-β1- and hypoxia-inducible RNF144A-AS1 promoted tumor metastasis, angiogenesis, and proliferation through targeting the miR-30c-2-3p/LOX axis in GC, highlighting the value of the RNF144A-AS1/miR-30c-2-3p/LOX axis in therapeutic interventions of GC." (PMID 34583752, 2021). "Nude mice (n=4) were injected with rhLOX protein (LOX recombinant protein; 25 ug/kg) by peritoneal injection before and after the tail vein injection of tumor cells within 3 weeks." (PMID 35003355, 2021). "The spectrum of LOX activity is wide and it includes the cross-linking of elastin and collagen fibers, the modulation of the structure and stiffness of tumor ECM19,20, and the regulation of cell migration and adhesion." (PMID 33658580, 2021). "Western blot analysis confirmed higher levels of LOX expression in the MDA-MB-231 tumor microenvironment compared to those of the MDA-MB-231 tumors treated with the LOX inhibitor or the MCF-7 tumors." (PMID 34572752, 2021). "Here, we found that LOX was highly expressed in the same region of CAFs distribution in tumor stroma, and there was a statistical correlation between the two." (PMID 34930321, 2021). "In this study, AuNPs functionalized with LOX-sensitive peptides were introduced to detect the LOX levels in both in vitro and tumor tissue extracts." (PMID 34572752, 2021). "Here, we investigated the role of lysyl oxidase (LOX) expression in CAFs in tumor stromal remodeling and the mechanism of its effect on OSCC progression." (PMID 34930321, 2021). "LOX is involved in regulating tumor cell proliferation, supporting metastasis and plays an important role in tumorigenesis and progression." (PMID 35003355, 2021). "Accumulated studies suggest that LOX is closely related to tumor cell proliferation, migration, invasion, and metastasis and is perhaps a potential molecular target for tumor therapy." (PMID 35047494, 2021). "Considering the expression level of LOX family in GC tumor tissues and their prognostic values in GC, LOX and LOXL2 were taken into next functional enrichment analysis." (PMID 35126449, 2021). "Cancer cells secrete the ECM regulators and other factors to maintain the tumor ECMs, for example, LOX, LOXL2, LOXL4 & PLOD1, S100-A4, S100-A6 & S100-A13." (PMID 34821729, 2021). "In vitro and in vivo models showed LOX stimulates endothelial cell division and drives tumor angiogenesis through the activation of the Akt-VEGF pathway in CRC." (PMID 34502094, 2021). "The lysyl oxidase (LOX) family of enzymes are a major driver in the biogenesis of desmoplastic matrix at the primary tumour and secondary metastatic sites." (PMID 33513979, 2021). "In response to hypoxia, the LOX protein level increases in tumor cells, andsuppression of LOX expression/ activity prevents metastasis." (PMID 33959388, 2021). "TM has been demonstrated to inhibit angiogenesis in tumours by targeting multiple pathways including the suppression of NF-κB, HIF1α, LOX and SOD1 activities." (PMID 34604310, 2021). "We then examined the effect of LOX inhibition on tumor stiffness and on the presence of stiff regions." (PMID 34106045, 2021). "LOX-induced collagen cross-linking is an important mediator of increased matrix stiffness in tumors and a driver of metastatic tumor growth." (PMID 34956223, 2021). "PLGA-based LOX-traceable NPs consisting of LOX antibodies and paclitaxel were successfully synthesized and can be used as a tumor-targeting drug carrier for chemotherapy and targeted radiotherapy." (PMID 33968752, 2021). "It was postulated that losartan inhibited tumor metastasis by reducing LOX- and collagen I-mediated integrin signal transduction." (PMID 33391538, 2021). "In a PTEN-null glioblastoma xenograft mouse model, LOX inhibition decreases macrophage infiltration and tumor growth." (PMID 34503065, 2021). "This study highlights the application of peptide-functionalized gold nanoprobes for sensing the LOX levels in tumor microenvironments." (PMID 34572752, 2021).